SOX2 (SRY-box transcription factor 2)
Diseases named in the same sentence as SOX2 in open-access papers (continued):
Sharing a sentence is not in itself a finding about the gene and the disease.
tumor (continued). "The results showed that IL-17B induced the expression of stemness-related genes Nanog, Sox2, and Oct4 in mesenchymal stem cells and enhanced its tumor-promoting effect." (PMID 28145881, 2017). "Going forward, it will be important to reexamine the effects of SOX2 in other cancers using inducible overexpression of SOX2, in particular where stable overexpression has been reported to increase tumor cell growth." (PMID 28388544, 2017). "Again, we observed that several factors were expressed both by tumour and host cells in the tumour core, including Musashi-1 and SOX2." (PMID 28173797, 2017). "In BMSCC, SOX2 is expressed within the tumor nests, the peritumoral stroma and the endothelium of the microvessels within the peritumoral stroma." (PMID 28626726, 2017). "In a previous study, we demonstrated that silencing SOX2 by siRNA induced G1 cell cycle arrest mediated by upregulation of CDKN1A expression resulting in an anti tumor effect in SOX2-expressing lung SCC cells both in vitro and in vivo." (PMID 29262545, 2017). "In several cancers, SOX2 expression increases during tumor progression, but, paradoxically, experimentally increasing SOX2 expression on its own in tumor cells with the aid of an inducible promoter leads to a reduction in growth." (PMID 28388544, 2017). "miR-145 is established as a tumor suppressor, targeting embryonic transcription factors including Lin28, Nanog, Sox2 and Oct417, 18, 19 in various cancer models." (PMID 28703793, 2017). "It is evident from the discussion in this section that there is a clear need for further investigation into the clinical implications of SOX2 expression, particularly how SOX2 levels influence tumor progression and patient survival." (PMID 28388544, 2017). "More recently, we have shown that inducible overexpression of SOX2 in multiple tumor cells, including three PDAC cell lines, leads to growth inhibition." (PMID 28388544, 2017). "This last topic addresses what we believe is a defining feature of SOX2: its levels in actively proliferating tumor cells appear to be optimized to maximize tumor growth; namely, too little or too much SOX2 inhibits tumor cell proliferation." (PMID 28388544, 2017). "For several tumor types, knockdown of SOX2 and/or ectopic expression of SOX2 have been used to implicate SOX2 in the biology of the TIC." (PMID 28388544, 2017). "As part of this discussion, we address the developing connection between SOX2 expression and tumor drug resistance." (PMID 28388544, 2017). "SOX2 overexpression has been correlated with breast cancer tumor grade, suggesting that it contributes to tumor aggression." (PMID 28929082, 2017). "In the case of cancer, at least 18 miRs have been reported to regulate SOX2 expression in tumor cell lines." (PMID 28388544, 2017). "In the group of aCP, a nuclear staining for Sox2 within the tumour tissue was hardly detectable as well." (PMID 29158570, 2017). "Many studies have used stable overexpression and/or knockdown of SOX2 in tumor cell lines to better understand the roles of this transcription factor in cancer." (PMID 28388544, 2017). "Since SOX2 is a marker of stem-like and dedifferentiated tumor cells, activation of SOX2 can contribute to increased invasiveness of lung tumors in FoxM1-ΔN transgenic mice." (PMID 29267283, 2017). "SOX2 is a transcription factor essential for maintaining the tumorigenic ability of CSC in different tumor types." (PMID 28036292, 2017). "IHC analysis confirmed that these tumors express less YAP1 and also show greatly reduced SOX2 and Ki67 protein levels, suggesting that both tumor cell proliferation and the number of progenitor/stem like cells are regulated by YAP1 expression in vivo." (PMID 29383141, 2017). "In contrast to previous results in HNSCC, SOX2 seems to promote invasion and tumor progression by creating a more mesenchymal phenotype in ACCs." (PMID 28671620, 2017).
tumor (continued). "Upon SOX2 knockdown, the number of tumours seeded in the lung are significantly reduced (33 ± 2 Vs 7 ± 3) (p < 0.001) (n = 5)." (PMID 28288641, 2017). "For SOX2, some studies were consistent with our results and reported a better outcome of HNSCC patients with high SOX2 expression levels in the primary tumor." (PMID 28002801, 2017). "The GSEA assay in the study revealed that the Sox2-targeted gene set was enriched in poorly differentiated tumors, and that Sox2 expression was correlated with tumor differentiation, grade and recurrence in CRC specimens." (PMID 29228716, 2017). "Second, there is growing evidence that SOX2 also influences the responses of tumor cells to drugs used in the treatment of cancer." (PMID 28388544, 2017). "Cellular plasticity is inherent to tumor evolution, rendering cells that acquire a stem cell‐like phenotype, for which Sox2 activation has proved instrumental for the plastic acquisition of stemness properties in tumor cells." (PMID 28191771, 2017). "In the future, it will be important to characterize the post-translational modifications of SOX2 in tumor cells." (PMID 28388544, 2017). "High levels of SOX2 closely correlate with multiple processes during tumour development, including initiation, maintenance, invasion and metastasis." (PMID 28288641, 2017). "VDAC1-based peptide tumor treatment eliminated GSCs, as reflected in the marked decrease in the expression levels of all tested stem cell markers, namely Sox2, Nestin, CD133, Klf4, S100B and NGFR." (PMID 28412744, 2017). "Nevertheless, in addition to shifting the balance in favor of epithelial gene programs, miR-200s have been found to negatively regulate self-renewal gene networks, by targeting BMI1 or SOX2 and thereby limiting the growth of normal and tumor cells." (PMID 29137351, 2017). "Bmi1 and Klf4 were negatively related to aggressive tumor characteristics and highly expressed in hormone receptor-positive tumors – the opposite findings to those for Oct4 and Sox2." (PMID 28422735, 2017). "Recently, some typically expressed embryonic stem cells markers have been considered as the markers for tumor-initiating cells, such as c-Myc, SOX2, and OCT-4." (PMID 28408882, 2017). "Additional studies have indicated that linc-ROR regulates tumor stem cell differentiation, and promotes tumor cell proliferation, invasion and metastasis by regulating Oct4, Sox2, and Nanog expression via interfering with micro RNA-145." (PMID 29050257, 2017). "To investigate PTPRZ1 expression pattern in GBMs, we co-immunostained PTRPZ1 and several GSC markers in frozen GBM specimens and found a preferential expression of PTPRZ1 in tumour cells expressing GSC markers SOX2, OLIG2 and CD133." (PMID 28569747, 2017). "In the majority of these cancers, SOX2 has been reported to have increased expression or gene amplification in tumor tissue; however, the effects of SOX2 on tumorigenicity, prognosis, and drug resistance in human cancer have only begun to be explored." (PMID 28388544, 2017). "Celecoxib treatment also decreased the expression levels of Wnt pathway components and target genes, such as β-catenin, p-GSK-3β, MMP-2, Survivin, AXIN2, CYCLIN-D1 and C-MYC, and the CSC marker SOX-2 in the xenograft tumor tissues." (PMID 29383157, 2017). "The function of tumor suppressor miR-625 is at least partially related to targeting and repressing SOX2." (PMID 28129648, 2017). "In summary, the stem cell transcription factors Sox2 and Sox9 seem to play essential roles not only in the formation of CP but also in processes involving the tumour surrounding brain parenchyma." (PMID 29158570, 2017). "Among the other transcription factors of ESCs evaluated in this study, Sox2 was positively related to tumor aggressiveness, along with Oct4." (PMID 28422735, 2017). "Oct4, Sox2, Nanog, Bmi1, and Klf4 were expressed in 15.4%, 10.3%, 20.4%, 50.5%, and 17.6% of tumor samples, respectively." (PMID 28422735, 2017).
tumor (continued). "Meanwhile, disrupting PTN in MLCs reduced the proportion of SOX2+ tumour cells in the xenografts co-implanted with GSCs and shPTN MLCs (P<0.01, ANOVA test), suggesting that TAM-secreted PTN promoted GSC maintenance." (PMID 28569747, 2017). "Studies have demonstrated that Sox2 can enhance the function of YAP1 thus maintain the stemness of tumor cells." (PMID 29296212, 2017). "The frequency of OLIG2-positive cells varied in the different tumor cultures as did the expression of SOX2." (PMID 28148893, 2017). "We also call attention to an under-appreciated property of SOX2, its levels in actively proliferating tumor cells appear to be optimized to maximize tumor growth - too little or too much SOX2 dramatically alters tumor growth." (PMID 28388544, 2017). "More recently, we have observed the same effect on tumor growth when SOX2 was elevated in a second PDAC cell line (Wuebben and Rizzino, unpublished results)." (PMID 28388544, 2017). "Recognizing how SOX2 expression is altered between normal and tumorous tissues is important for understanding molecular changes necessary for tumor initiation and progression." (PMID 28388544, 2017). "IF IHC staining showed the presence of a SOX2+/NANOG+/KLF4+/c-Myc+/OCT− CSC subpopulation within the tumor nests, and a SOX2+/NANOG+/KLF4+/c-Myc+/OCT4− CSC subpopulation and a SOX2+/NANOG+/KLF4+/c-Myc+/OCT4+ CSC subpopulation within the peritumoral stroma." (PMID 29404335, 2017). "Sox2 was reported as a tumor suppressor that inhibits cell growth by either regulating cyclin D1, phosphorylated Rb, or p27 (Kip1) levels, or directly activating PTEN." (PMID 28046028, 2017). "By contrast, other studies found a worse prognosis for HNSCC patients with high SOX2 expression in the primary tumor." (PMID 28002801, 2017). "SOX2 is a stemness gene of ESCC, is required for ESCC cell growth, and that SOX2 overexpression in esophageal epithelial cells induces migration and transforms growth and tumor formation in vivo." (PMID 28404917, 2017). "Accordingly, we propose that SOX2 levels in actively proliferating tumor cells are optimized to maximize tumor growth: too little or too much SOX2 decreases tumor growth and alters cell behavior." (PMID 28388544, 2017). "Our experiments demonstrated that SH down-regulated CD44 and Sox-2 expression in primary tumor specimens and metastatic lung specimens." (PMID 28088791, 2017). "To determine the percentage of SOX2-positive cells in tumor samples, we performed immunocytochemistry assays in tumor cells isolated from 11 patients and found that the percentage of SOX2-positive cells varies from 10% to 60%." (PMID 28934267, 2017). "We suggest that two factors, which are not mutually exclusive, are likely to contribute to the apparent increase in SOX2 expression during tumor progression." (PMID 28388544, 2017). "Downregulation of pluripotency marker SOX2 expression led to inhibited tumor growth and a reduced capacity of cancer cells to induce tumor growth when injected subcutaneously in several serial dilutions." (PMID 27845900, 2017). "Functionally, NFATc2/SOX2 coupling contributes to tumor behavior as depletion of SOX2 in cell lines with NFATc2 overexpression led to significant suppression of TIC phenotypes." (PMID 28737489, 2017). "The expressions of CD44, CD133, SOX2 and Nanog were correlated with histological grade and tumor stage for MEC of the palate respectively." (PMID 28262804, 2017). "In at least three cancers, SOX2 has been shown to be expressed by the cancer stem cell/tumor-initiating cell population of the tumor." (PMID 28388544, 2017). "There is growing evidence for a population of anterior pituitary stem cells expressing Sox2 that can give rise to the main anterior pituitary progenitor cell lineages and that, crucially, also have tumour-inducing potential." (PMID 28781761, 2017). "Immunohistochemical (IHC) analysis showed diffuse expression of GFAP, OLIG2 and SOX2 consistent with a tumor of glial lineage." (PMID 26817999, 2016).
tumor (continued). "We report here a mouse model system, in which the artificially induced constitutive activation of the canonical Wnt signaling pathway at E14.5 drives the formation of tumor-like OE lesions from Sox2-positive precursors of the OE structure." (PMID 27902722, 2016). "Relevant CSC-related factors, such as ALDH1 and SOX2, were increasingly upregulated in CSCs during tumor progression, and importantly, the increased levels and activity of ALDH1 in these subpopulations were associated with enhanced tumorigenicity." (PMID 27292183, 2016). "Positive staining for pSTAT3 (brown), SALL4 (brown), and SOX2 (brown) was observed in tumor cells and within areas of endothelial proliferation." (PMID 27617262, 2016). "We next examined the expression of SATB2, Oct-4, Nanog, c-Myc and Sox-2 in tumor tissues harvested from HPNE/SATB2 groups by immunohistochemistry." (PMID 27472393, 2016). "FASN immunoreactivities were detected in the cytosol in tumor cells, while those of Sox2 were confined to the nuclei." (PMID 26808816, 2016). "Using a median cutpoint based on the gene expression values of Pax7 and Sox2, we plotted PAs according to the high or low expression of these genes relative to the rate of secondary tumor sphere formation." (PMID 27894339, 2016). "In SqCC, CD44, ALDH1, SOX2 and Nanog were expressed in 88.0%, 73.2%, 71.1%, and 92.2% of tumor cells, respectively." (PMID 27285762, 2016). "Having a dynamic Sox2 population makes this an excellent model in which to test the effect of drugs on the tumor stem cell population." (PMID 26659251, 2016). "When investigating the SKCM dataset, we found SOX9, SOX2 as well as SOX6 to be down-regulated in the tumor subgroup of low SOX5 expression compared to the tumor subgroup of high SOX5 expression." (PMID 26927636, 2016). "FGFR2 KD decreased most GCSC marker expression, including CD44, but increased c-Myc and Sox2 expression and attenuated tumor growth." (PMID 27107424, 2016). "SOX2 not only influences tumor growth, it also influences responses of tumor cells to drugs used clinically." (PMID 27145457, 2016). "If SOX2 levels must be maintained within optimal limits to promote tumor growth, how can SOX2 levels rise during tumor progression?" (PMID 27145457, 2016). "Similar to ALDH1, our results show that SOX2 is upregulated in CSC subpopulations during tumor evolution." (PMID 27292183, 2016). "ACE (green, arrows) was expressed on the endothelium of the microvessels within the peri-tumoral stroma, which expressed SOX2 (red), distinct from the tumor nests." (PMID 27730124, 2016). "SP cells showed higher tumor-initiating ability and SP cell showed higher expressions of stem cell-related genes including SOX2, ALDH1A1, KLF4 and NANOG, indicating that SP cells are enriched with CSCs/CICs." (PMID 27418136, 2016). "The accumulation of salmonella and co-expression of Sox2 shRNA enhanced the therapeutic effect of HM-3 on the growth of tumor." (PMID 27371094, 2016). "This decrease in tumor outgrowth was accompanied by a decrease in Cyp1b1, Aldh1a1, and Sox2 expression, further linking AHR activity to expression of these genes." (PMID 26984638, 2016). "Since SOX2 is a key driver in the maintenance of the GSCs phenotype and therefore in the perpetuation of this devastating tumor we down-regulated the expression of this gene in the GSC11 cell line in four independent experiments, using a SOX2 specific siRNA." (PMID 27669421, 2016). "The detection of a EMA+/CD44+/SOX2+/OCT4+/SALL4+/pSTAT3+/NANOG+ subpopulation within the tumor nests aligns with recent literature reporting localization of CSC in OCSCC, particularly at the “tumor front”." (PMID 27532037, 2016). "In prvious documents, BMI1 and SOX2 were the key tumor stemness factors, which had been documented as the direct targets of miR-200 family members." (PMID 27589832, 2016). "Stable overexpression of SOX2 in cell lines derived from many types of cancer has been reported to increase tumor cell growth in vitro and in vivo." (PMID 27145457, 2016).
tumor (continued). "Reduction in CD133 expression inhibits tumor cell proliferation, colony formation and the expression of Nanog, Oct4, Sox2 and c-Myc stemness transcription factors." (PMID 27898034, 2016). "We determined the expression level of NICD1 and stemness factors, such as NANOG, OCT4 and SOX-2 in tumor sections prepared galectin-3 overexpressing A2780 cells." (PMID 27626163, 2016). "We plan to further investigate the role of SOX2 in cancer stem cell differentiation and tumor progression." (PMID 27411517, 2016). "Second, TICs of any tumor highly express embryonic stem factors, such as Oct-4, Nanog, Sox2, and Klf4." (PMID 26695440, 2016). "Real-time qPCR revealed that OCT-4 and SOX-2 mRNAs are expressed in hMSCs and their expression is very low when compared with tumor cell lines used as a positive control." (PMID 27275321, 2016). "In 92% of SQCCs, some P-S6 staining was detectable, and 91% of SQCCs that expressed SOX2 also expressed P-S6, although in many cases, few tumor cells expressed P-S6." (PMID 27880766, 2016). "SOX2 staining showed strong nuclear staining in tumor cells that lessened in intensity within areas of endothelial proliferation, with a consistent, moderate level of cytoplasmic staining throughout the entire sample (brown)." (PMID 27617262, 2016). "SOX2 expression was increased in tumor spheres, and overexpression of SOX2 stimulated CSC properties including stemness marker expression, sphere formation, in vivo tumorigenicity, and resistance to apoptosis." (PMID 27489349, 2016). "All these signaling pathways are aberrantly activated in GBM, which leads to the maintenance of the tumor at least in part through SOX2 factor overexpression." (PMID 27822457, 2016). "In 21/27 node-positive PC cases a distinct to strong SOX2 expression was observed in the lymph node metastases, as seen in the primary tumor." (PMID 26540632, 2016). "The expression of Sox2 was down regulated in the tumor tissue of the combined treatment group of HM-3 with VNP20009 carrying the Sox2 shRNA construct." (PMID 27371094, 2016). "The expression of Sox-2 was reduced in the periphery for all tumor grades and subtypes except for the Anaplastic Oligodendroglioma (AO), but without reaching significance." (PMID 27171431, 2016). "Immunohistochemistry showed that IR-induced IL-4 increased the expression of major components related to p-Stat6, mesenchymal trait marker, Vimentin; invasiveness marker, MMP-9; stemness maintenance marker, Sox2; and tumor proliferation marker, Ki-67." (PMID 27895317, 2016). "The mRNA levels of pluripotency genes, Nanog and SOX-2, tumorsphere formation ability, tumor growth, and lung metastasis of SC-M1 cells were elevated by activated Notch1 pathway through miR-151-5p." (PMID 27191259, 2016). "CD44 knockdown (KD) depleted FGFR2 and other GCSC markers, decreased c-Myc and Sox2 expression, and suppressed tumor growth, whereas CD44 activation led to FGFR2 induction." (PMID 27107424, 2016). "In the work presented in our study, we not only demonstrate that knockdown of SOX2 reduces growth in vitro, we also demonstrate that tumor growth of i-KdSOX2-L3.6 cells is reduced when SOX2 is knocked down in vivo." (PMID 27145457, 2016). "In BC, it was found that over-expression of Sox2 increased mammosphere formation whereas knockdown of Sox2 delayed tumour formation in xenograft tumour initiation models." (PMID 26683522, 2016). "Sox2 depleted cells exhibit increased Hippo signaling, a tumor suppressive pathway that restrains YAP function and that is inactivated in several cancers." (PMID 27528232, 2016). "A similar staining pattern was also seen with SOX2 for cells within the tumor nests (red) and the stroma (red), and the endothelium marked by CD34 (green)." (PMID 27532037, 2016). "Our in vivo animal studies indicate that treatment of an established GBM xenograft tumor with cyclic-RGD-peptide significantly increased the mean distance of Sox2-positive tumor cells from ECs as compared to controls." (PMID 27270311, 2016).